CAMP (cathelicidin antimicrobial peptide)
Diseases named in the same sentence as CAMP in open-access papers (continued):
Sharing a sentence is not in itself a finding about the gene and the disease.
acne (12 papers, 2010 to 2025). An inflammatory process of the sebaceous glands which is characterized by comedones, nodules, papules and/or pustules on the skin. "In a mouse model of acne, mutation of the Christie-Atkins-Munch-Petersen factor (CAMP, a secretory factor of C. acnes) or vaccination with CAMP factor antibodies reduces C. acnes colonization and C. acnes-mediated inflammation." (PMID 37344849, 2023). "This comparison underscores the potential functional diversity of CAMP factors, which may contribute to their varying pathogenic roles in acne development." (PMID 40668089, 2025). "Targeting specific CAMP factors and their associated inflammatory pathways may offer a promising strategy for acne treatment and prevention of recurrence." (PMID 40668089, 2025). "Furthermore, recent studies suggest that C. acnes may enhance its virulence in synergy with CAMP factors secreted by acne-associated strains, warranting further investigation." (PMID 40668089, 2025). "Despite low sequence homology between CAMP factors from C. acnes and other bacteria, these proteins are expressed at significantly higher levels in acne lesions compared with non-acne skin." (PMID 40668089, 2025). "Supporting this, previous research has demonstrated that monoclonal antibodies against the C. acnes CAMP factors significantly reduced IL-8 production in inflamed acne tissues, further validating CAMP as a driver of cytokine-mediated inflammation." (PMID 40668089, 2025). "Our functional comparison of four putative CAMP factors revealed distinct haemolytic properties, adding a new dimension to our comprehension of the molecular mechanisms driving acne." (PMID 40668089, 2025). "Nonetheless, the interplay between CAMP and IL-8 highlights their potential as synergistic therapeutic targets for modulating acne-related inflammation." (PMID 40668089, 2025). "While this study provides valuable insights into the role of C. acnes and its CAMP factors in acne pathogenesis, several limitations should be acknowledged." (PMID 40668089, 2025). "Together, these findings clarify the functional diversity of C. acnes CAMP factors and highlight potential new avenues for targeted acne therapy." (PMID 40668089, 2025). "Known for their involvement in the CAMP reaction, we examined their haemolytic activity on red blood cells pretreated with sphingomyelinase, at the pH of acne-affected skin (~6.5)." (PMID 40668089, 2025). "The most abundant P. acnes proteins were surface-exposed dermatan sulphate adhesins, CAMP factors, and a so far uncharacterized lipase in follicular casts extracted from normal as well as acne-affected skin." (PMID 25238151, 2014). "This work has identified both CAMP factor and ASMase as potential molecular targets for the development of drugs and vaccines against acne vulgaris." (PMID 21533261, 2011). "Here, we examined cytotoxic activity of P. acnes CAMP factor on host cells, and its physiologic relevance to the pathogenicity of P. acnes, which is highly relevant to severe inflammatory acne vulgaris." (PMID 21533261, 2011). "While elevated levels of CAMP factors and inflammatory cytokines have been observed in acne lesions, the specific contributions of CAMP proteins to disease pathogenesis remain incompletely understood, underscoring the need for further mechanistic investigation." (PMID 40668089, 2025). "The vaccine was found to reduce C. acnes colonization and inflammation; vaccine-induced antibodies against CAMP factor suppressed the inflammatory response to C. acnes in mice and ex vivo in human acne explants, suggesting a role for CAMP factor in inflammation." (PMID 40006672, 2025). "Interestingly, a recent study reported the efficacy of CAMP factor antibodies in the neutralization of the acne inflammatory response inex vivo acne models; the incubation ofex vivo acne skin explants from acne patients with monoclonal antibodies (mAbs) to theP." (PMID 30613388, 2018).
acne (continued). "In addition, desipramine may have a therapeutic potential for acne by blocking the synergistic cytotoxicity of P. acnes CAMP factor and host ASMase." (PMID 21533261, 2011). "Clinically, acne lesions exhibit higher levels of CAMP factor and TLR2 than nonlesional skins, further substantiating that the CAMP factor of C. acnes is a key contributor to TLR2-related inflammation in acne." (PMID 37344849, 2023).
shigellosis (12 papers, 2011 to 2025). Shigellosis is a bacterial infection leading to dysentery and is caused by Shigella, which are small, ubiquitous Gram-negative bacteria belonging to the enterobacteria family. "Consistent with their HDP-inducing activity in cells, oral supplementation of sodium butyrate or PBA improved the clinical outcomes of shigellosis in both humans and rabbits by counteracting Shigella-induced downregulation of CAMP expression in the intestinal tract." (PMID 39053604, 2024).
periodontal disease (11 papers, 2014 to 2025). "In addition, this study might suggest that the suppression of hydrolytic activity of BANA in periodontal pathogens and the increased concentration of salivary CAMP explain in part the therapeutic effects of AGE in periodontal diseases in animals and humans." (PMID 38026667, 2023).
malignant melanoma (10 papers, 2016 to 2025). "Previously we also demonstrated synergistic effects of NE/CAMP and ICIs in treating melanoma in mouse models." (PMID 39801750, 2025). "Moreover, the adoptive transfer of CAMP‐activated NEs (NE/CAMPs) induced robust anti‐tumor systemic immune response through activation of immune cells and suppressed tumor growth in mice burdened with breast cancer and melanoma tumors." (PMID 39801750, 2025).
skin infection (10 papers, 2012 to 2025). An inflammatory process affecting the skin, caused by bacteria, viruses, parasites, or fungi. "Host acid sphingomyelinase enhances cytotoxic and inflammatory properties of P. acnes CAMP factor in vitro and in skin infection models." (PMID 34908468, 2021). "During Staphylococcus aureus skin infection, the dermal fibroblasts differentiate into adipocytes and produce AMP, mainly CAMP, for host defense." (PMID 39536069, 2024).
respiratory infections (9 papers, 2015 to 2024). "Suppression of CAMP by HCA may increase the risk for recurrent respiratory infections in neonates exposed to HCA." (PMID 30971730, 2019).
Arthritis (8 papers, 2014 to 2026). Inflammation of a joint. "Treatment with CAMP derivatives (CED) showed significant anti-inflammatory effects with CED at doses 50 mg\kg and 100 mg\kg in an experimental rat model of arthritis." (PMID 38322703, 2023).
fungal infection (8 papers, 2011 to 2024). "From our studies, it can be inferred that initial production of IL-1β may induce IL-17A and CAMP production which can in turn positively regulate further production of IL-1β to create an inflammatory environment which limits fungal infection." (PMID 22174673, 2011).
Alzheimer disease (7 papers, 2021 to 2026). A progressive, neurodegenerative disease characterized by loss of function and death of nerve cells in several areas of the brain leading to loss of cognitive function such as memory and language. "Notably, our analysis suggests a potential association between CAMP and Alzheimer’s disease, which is further supported by in-depth bioinformatics analysis." (PMID 38350848, 2024). "Therefore, it is reasonable for M-GBBD to identify CAMP as highly associated with Alzheimer’s disease." (PMID 38350848, 2024). "Importantly, the generalizability and accuracy of M-GBBD are confirmed by large-scale cohort GWAS studies, where we identify CAMP as a potential candidate gene associated with Alzheimer's disease." (PMID 38350848, 2024). "Furthermore, our analysis supported by bioinformatics revealed CAMP as a significantly associated gene with Alzheimer's disease identified by M-GBBD." (PMID 38350848, 2024). "This extended signature includes granule proteins CAMP, CTSG, DEFA3, and MPO secreted from neutrophils and points to olfactomedin 4 (OLFM4) as a new target for the prevention of Alzheimer's disease." (PMID 41316897, 2026). "The signature supports the role of APOE in lipid regulation through apolipoproteins and inflammation and includes, among others, neutrophil secreted granule proteins CAMP, CTSG, DEFA3, and MPO that point to inhibition of OLFM4 as a target for Alzheimer's disease therapeutics." (PMID 41316897, 2026). "Resveratrol is a non-flavonoid polyphenol that can induce neuroprotection in Alzheimer's disease and other cognitive disorders through modulating the CAMP/AMPK/SIRT1 pathway." (PMID 40718448, 2025). "Interestingly, HAVCR2 and CAMP demonstrate higher scores compared to other genes, suggesting that M-GBBD has potential for predicting potential Alzheimer's disease-associated genes not yet annotated by DisGeNET." (PMID 38350848, 2024). "Although direct experimental evidence supporting the association between CAMP and Alzheimer's disease is currently lacking, microarray analysis (GSE85426), which included 90 patients with Alzheimer's disease and 90 controls, revealed significant changes in CAMP expression levels." (PMID 38350848, 2024).
chronic obstructive pulmonary disease (7 papers, 2018 to 2023). A chronic and progressive lung disorder characterized by the loss of elasticity of the bronchial tree and the air sacs, destruction of the air sacs wall, thickening of the bronchial wall, and mucous accumulation in the bronchial tree. "Additionally, in chronic obstructive pulmonary disease (COPD) patients’ levels of CAMP and other antimicrobial peptides were associated with increased risk of acute exacerbations." (PMID 30400332, 2018).
myocardial infarction (7 papers, 2017 to 2024). Gross necrosis of the myocardium, as a result of interruption of the blood supply to the area, as in coronary thrombosis. "Human serum cathelicidin antimicrobial peptide (LL-37) levels were measured in myocardial infarction (MI) patients." (PMID 30782145, 2019). "Since myocardial infarction results in hypoxemia, hypoxic effects might also play a role in modulating circulating CAMP/CRAMP levels in our experimental models." (PMID 38474156, 2024).
type 2 diabetes (7 papers, 2011 to 2024). "Here, we show that higher levels of proinflammatory cytokines and CAMP, encoding for the antimicrobial peptide cathelicidin, LL-37, correlate with HIF-1 in type 2 diabetic patients." (PMID 34651203, 2022). "Furthermore, higher levels of proinflammatory cytokines and CAMP correlate with HIF-1 in type 2 diabetic patients." (PMID 38474156, 2024).
colorectal cancer (6 papers, 2013 to 2026). A primary or metastatic malignant neoplasm that affects the colon or rectum. "Ethnicity-dependent VDR activity, as reflected in CAMP gene expression, may explain differential disease predisposition, as illustrated by the higher prevalence of TB and colorectal cancer in Africans compared to Whites." (PMID 23805323, 2013). "In contrast, the expression of the CAMP gene and levels of LL-37 secretion are significantly decreased in gastric and colorectal cancers, oral squamous cell carcinoma, leukemia, lymphoma and SH-SY5Y neuroblastoma cells." (PMID 35956937, 2022). "Previous research has shown that LL-37 secretion levels and CAMP gene expression are significantly reduced in colorectal cancer, glioma, and SH-SY5Y neuroblastoma." (PMID 39339270, 2024).
dermatitis (6 papers, 2017 to 2025). An inflammatory process affecting the skin. "Th17 cell-associated genes, (i.e., S100a8, CAMP, BATF, IL-23A, LCN2, and HIF-1α) highly expressed in Nfkbiz−/− mice with dermatitis, were downregulated after antibiotic treatments." (PMID 28740238, 2017). "It seems that vitamin D analogs may ameliorate skin inflammation through pathways other than CAMP expression, and our treatment consequences may inhibit the effect of upregulated Camp in the development of the psoriatic manifestations." (PMID 39045230, 2024). "Furthermore, IL-17A target genes (i.e., S100a9, S100a8, CAMP, and LCN2) were remarkably upregulated in the skin of Nfkbiz−/− mice with dermatitis." (PMID 28740238, 2017). "However, in this study, we observed robust Th17 responses as well as expression of IL-17A signature genes (i.e., S100a8, S100a9, CAMP, and LCN2) in the skin of Nfkbiz−/− mice with spontaneous dermatitis." (PMID 28740238, 2017).
hepatocellular carcinoma (6 papers, 2022 to 2025). A malignant tumor that arises from hepatocytes. "Hepatocellular carcinoma tumor tissues have insignificantly lower levels of CAMP mRNA expression compared to those in normal liver tissues according to the Gene Expression Profiling Interactive Analysis (GEPIA) and UALCAN databases." (PMID 37958632, 2023).
HIV-1 infection (5 papers, 2017 to 2019). The type species of lentivirus and the etiologic agent of acquired immunodeficiency syndrome (AIDS). "In this regard, VitD might also protect against HIV-1 infection through induction of an antiviral response mainly mediated by CAMP and APOBEC3G molecules." (PMID 31550271, 2019).
inflammatory bowel disease (5 papers, 2019 to 2026). A spectrum of small and large bowel inflammatory diseases of unknown etiology. "Levels of CAMP are increased in the mucosa of inflammatory bowel disease (IBD) patients." (PMID 32692761, 2020).
legionellosis (5 papers, 2023 to 2025). Any disease caused by Legionella bacteria. "The groups exhibited significant differences in pathways associated with Arrhythmogenic right ventricular cardiomyopathy (ARVC), Cationic antimicrobial peptide (CAMP) resistance, Chemical carcinogenesis, Legionellosis, Pertussis, and Proteoglycans in cancer." (PMID 40474978, 2025).
Obesity (5 papers, 2011 to 2024). Accumulation of substantial excess body fat. "In mice, diet-induced obesity results in the loss of a dermal pool of preadipocytes and thus inhibits the capacity to initiate reactive adipogenesis and to express CAMP." (PMID 37958808, 2023). "A possible interaction between CAMP expression, TNFα, and cfDNA in adipocytes and adipose tissues might provide a novel molecular interface of obesity-related inflammation with adipocyte function." (PMID 37958808, 2023). "Among the metabolically healthy individuals participating in the present study, basal CAMP levels did not exhibit a significant sexual dimorphism—as was recently found in obese individuals —nor a significant impact of overweight and obesity (BMI ≥ 25 kg/m2)." (PMID 37629082, 2023). "Authors have speculated that small amount of lactose may not be absorbed and, via the CAMP-induction, contribute to infant gut homeostasis, protection against pathogens and regulation of gut microbiome, which has been implicated in the development of infant weight gain and obesity." (PMID 31261649, 2019).
allergic asthma (4 papers, 2017 to 2023). A asthma with a basis in a pathological type I hypersensitivity reaction. "Cathelicidin antimicrobial peptide (CAMP), as a bactericidal agent in allergic asthma are also increased in the absence of RELMβ." (PMID 36691020, 2023).
bladder cancer (4 papers, 2017 to 2024). "For the disease- and immunity-related pathways, “Bladder cancer”, “Non-alcoholic fatty liver disease”, “CAMP resistance”, and “Platinum drug resistance” were identified." (PMID 39125723, 2024). "The CAMP level was increased by over 8-10-fold in BCG-treating bladder cancer cells compared to untreated cells." (PMID 28881802, 2017). "These DEGs were mainly enriched for GO terms RNA polymerase II core promoter proximal region sequence and its DNA binding, and cAMP response element binding protein, and KEGG pathways including bladder cancer, thyroid cancer and PI3K-AKT signaling." (PMID 37556419, 2023).
heart failure (4 papers, 2023 to 2024). Inability of the heart to pump blood at an adequate rate to meet tissue metabolic requirements. "Investigating the possible role of CAMP in patients with heart failure therefore appears to be a promising goal for future research." (PMID 38474156, 2024). "We observed statistical relations between CAMP serum levels and compromised myocardial function as a sign of heart failure, i.e., decreased left ventricular ejection fraction." (PMID 38474156, 2024). "CAMP exhibits a complex role, as it can trigger platelet activation and blood clot formation in mice while also providing protection against cardiac fibrosis in diabetic mouse hearts, showing promise as a therapeutic target for heart failure." (PMID 38753730, 2024). "Therefore, CAMP might play a role in the development of heart failure." (PMID 38474156, 2024). "Signs of heart failure and LVEF decrease to <40% was recorded in 4 patients with elevated mRNA and protein expression of PGLYRP1, CAMP, MMP9 and CEACAM8 at baseline and after the initial chemotherapy dose." (PMID 39273682, 2024).
malaria (4 papers, 2017 to 2026). Malaria is a serious and sometimes fatal disease caused by a parasite that commonly infects a certain type of mosquito which feeds on humans. "By contrast, the CAMP allele was more prevalent in the > 10 years, an age group known to have acquired immunity against malaria." (PMID 33032613, 2020).
myocardial ischemia (4 papers, 2019 to 2024). A disorder of cardiac function caused by insufficient blood flow to the muscle tissue of the heart. "CAMP was found to aggravate inflammation-related myocardial ischemia/reperfusion (MI/R) injury in experimental mice." (PMID 39273682, 2024).
osteoarthritis (4 papers, 2021 to 2023). A noninflammatory degenerative joint disease occurring chiefly in older persons, characterized by degeneration of the articular cartilage, hypertrophy of bone at the margins and changes in the synovial membrane. "CAMP gene promoter methylation inhibits inflammation and induces chondrocyte apoptosis which is known to play a role in osteoarthritis." (PMID 36964402, 2023). "Our analysis in Human Chondrocytes Osteoarthritis (HC-OA) cells and Human Chondrocytes-articular (HC-A) cells showed that the CAMP mRNA level and CAMP protein level in HC-OA cells were significantly higher than those in HC-A cells (p < 0.001, p < 0.0001)." (PMID 33892795, 2021). "The results of this study suggested that the expression of CAMP gene and methylation in promoter region might be involved in the occurrence of osteoarthritis from the level of oxidative stress and the expression of inflammatory factors." (PMID 33892795, 2021). "CAMP was highly expressed in osteoarthritis articular cartilage cells." (PMID 33892795, 2021). "Silencing the expression of CAMP gene inhibited the proliferation of osteoarthritis articular cartilage cells and promoted their apoptosis, suggesting that CAMP may play an important role in the pathogenesis of osteoarthritis." (PMID 33892795, 2021). "Cell Counting Kit-8 (CCK-8) and flow cytometry analysis of short hairpin RNA (shRNA) silencing CAMP gene and 5-μM 5-Aza-2’-Deoxycytidine (AZA) treatment on the proliferation and apoptosis of Human chondrocytes osteoarthritis (HC-OA) cells." (PMID 33892795, 2021).
breast tumors (3 papers, 2009 to 2016). "Particularly in the breast, CAMP is abundantly produced in both normal and malignant conditions, while its maximum expression has been found among high-grade breast tumors." (PMID 27832772, 2016). "Interestingly, CAMP expression is closely correlated with that of epidermal growth factor receptor 2 (HER2) and with the presence of lymph node metastases in estrogen receptor (ER) + breast tumors, suggesting a prometastatic role for CAMP in breast malignancy." (PMID 27832772, 2016). "Since CAMP may regulate tumorigenesis and/or cell proliferation, more studies are needed in order to clarify exogenous calcitriol-dependent CAMP synthesis and biological actions in breast tumors with different phenotype." (PMID 27832772, 2016).